Y_RNA (Y RNA )
Gene: Miscellaneous RNA gene on chromosome 11 (47,820,200 to 47,820,289, reverse strand). Ensembl gene ENSG00000252874.
Homologues: Orthologues: chimpanzee Y_RNA (100% identical). Paralogues in human: Y_RNA (82% identical), Y_RNA (81% identical), Y_RNA (80% identical), Y_RNA (78% identical), RNY4 (77% identical), RNY4P19 (77% identical), RNY4P6 (77% identical), Y_RNA (77% identical), RNY4P29 (76% identical), RNY4P37 (76% identical), RNY4P9 (76% identical), Y_RNA (76% identical), and 87 more.